MALAT1 (metastasis associated lung adenocarcinoma transcript 1)
Diseases named in the same sentence as MALAT1 in open-access papers (continued):
Sharing a sentence is not in itself a finding about the gene and the disease.
breast cancer (continued). "Initially recognized as a biomarker for early-stage non-small cell lung cancer capable of predicting metastasis and survival, MALAT1 exhibits a complex role in breast cancer progression." (PMID 39997609, 2025). "The RIP analysis showed the binding of METTL14 to MALAT1 in breast cancer cells and the MeRIP-PCR assays indicated that METTL14 knockdown significantly reduced m6A modification of MALAT1 in BT474 cells." (PMID 40258843, 2025). "In the context of breast cancer, specifically in BT-474 cells, MALAT1 expression is upregulated, and reducing its expression can enhance the effectiveness of trastuzumab treatment." (PMID 41163216, 2025). "Its expression level has been found to be negatively correlated with breast cancer progression and metastatic ability, which contradicts the conclusions drawn from previous experiments that focused on the inhibition or knockdown of MALAT1." (PMID 40128064, 2025). "Among the numerous lncRNAs implicated in drug resistance, MALAT1, UCA1, CYTOR, and HOTAIR have emerged as crucial oncogenes, and GAS5 is a well‐known lncRNA that acts as a tumor suppressor in breast cancer." (PMID 41031251, 2025). "FOXO1 plays a regulatory role in mediating MALAT1 expression in breast cancer cells via the PI3K/Akt pathway." (PMID 40258843, 2025). "In vitro, MALAT1 expression was evaluated in breast cancer (MCF7) and normal breast (MCF10) cell lines via qRT‐PCR." (PMID 41031251, 2025). "Among the most studied lncRNAs in breast cancer are HOTAIR, UCA1, and MALAT1, which have been strongly implicated in tumorigenesis, metastasis, and therapy resistance." (PMID 40781106, 2025). "In breast cancer specimens and cell lines, it was discovered that MALAT-1 and TOP2A expressions were dramatically elevated, whereas miR-561-3p expressions decreased." (PMID 38511067, 2024). "Our results show that upon the knockdown of MALAT-1, a marked repression of STAT-3 and CSE was observed, thereby highlighting MALAT-1 as a novel upstream lncRNA regulating the STAT-3/CSE/ H2S axis in breast cancer." (PMID 38250807, 2024). "A sustained investigation into the engagement of MALAT1 in Breast Cancer is still imperative for the progression of our comprehension of this multifaceted ailment." (PMID 39323624, 2024). "Cell cluster_5 is also significantly associated with lncRNA-Topic 13, which includes MALAT1 and NEAT1 as top ranked genes, two lncRNAs extensively studied in breast cancer progression." (PMID 38611028, 2024). "MALAT1 was highly expressed in exhausted CD8+ T cells and was reported to be linked to breast cancer, pancreatic cancer, prostate cancer, glioma, and leukemia." (PMID 40453362, 2024). "Silencing METTL3 suppressed EMT by inhibiting MALAT1 expression, establishing the MALAT1/METTL3 axis of EMT in breast cancer." (PMID 40176927, 2024). "Some of the well-studied lncRNAs such as MALAT1 and NEAT1 are known for their causal impact on breast cancer metastasis." (PMID 38838009, 2024). "In breast cancer, lncRNA Malat1 promotes cell proliferation, inhibits cell apoptosis and destroys the tumour immune microenvironment." (PMID 39648148, 2024). "MALAT1, the snoRNA host genes SNHG16 and SNHG6, LINC00346 and LINC00511 are among VDR-associated lncRNAs identified through an in silico approach in breast cancer." (PMID 38475720, 2024). "Quercetin, a widely available dietary flavonoid, has been found to diminish the expression of lncRNA MALAT1 in breast cancer cell lines." (PMID 38505593, 2024). "Hypoxia-induced MALAT1 promotes the proliferation and migration of breast cancer cells by sponging miR-3064-5p." (PMID 38682035, 2024).
breast cancer (continued). "Knockdown of MALAT1 in these breast cancer cells also illustrated a decrease in cell proliferation, suggesting that high E2 doses reduced proliferation of breast cancer cells (ER-α) via reducing the expression of MALAT1." (PMID 39768369, 2024). "Compared with that in normal tissues, the expression of CDK4, HIF1A, and MALAT1 were upregulated in the breast cancer samples, which was consistent with the results of CARM1." (PMID 38476024, 2024). "The MALAT1, a huge non-coding RNA, recently came to light as a multifaceted regulator in the intricate landscape of breast cancer (BC) progression." (PMID 39323624, 2024). "This review focuses on experimentaland clinical studies into the role of MALAT1 in carcinogenesis and theprogression of breast cancer." (PMID 37538803, 2023). "Conversely, a more recent study showed that knocking out MALAT1 actually promotes metastasis in breast cancer, suggesting its role as a metastasis suppressant." (PMID 36902227, 2023). "The published data suggest that MALAT1 utilizes different mechanisms fordifferent molecular subtypes of breast cancer." (PMID 37538803, 2023). "MALAT1 expression levels aremuch higher in TNBC samples than they are in HER2+ breast cancer samples." (PMID 37538803, 2023). "For example, inhibition of the lncRNA MALAT1 triggered differentiation of breast cancer in animal models, suppressing tumorigenesis." (PMID 37239141, 2023). "Two other prominent examples of breast cancer linked lncRNAs are HOTAIR (HOX antisense intergenic RNA) and MALAT1 (Metastasis-associated lung adenocarcinoma transcript 1)." (PMID 37990044, 2023). "Previously, targeted inactivation and genetic rescue experiments identified MALAT1 as a suppressor of breast cancer lung metastasis." (PMID 36993303, 2023). "In subsequent studies, MALAT1 was found in several additional types of tumors, including breast cancer, correlating with poor prognosis." (PMID 37367050, 2023). "For instance, our work revealed that the nuclear lncRNA metastasis associated lung adenocarcinoma transcript 1 (MALAT1) directly binds TEAD to block its interaction with YAP and target gene promoters, thereby suppressing breast cancer lung metastasis." (PMID 38067201, 2023). "Examination of the roleof MALAT1 in breast cancer progression in the MMTV (mouse mammary tumorvirus)-PyMT model showed that MALAT1 knockdown subcutaneouslydelivered ASO and reduced the metastasis rate." (PMID 37538803, 2023). "In this study, we aimed to determine the correlation between miR-561-3p and MALAT1 and their roles in breast cancer progression." (PMID 37244966, 2023). "For instance, in a MMTV-PyMT breast cancer mouse model, subcutaneous delivery of Malat1 ASO led to metastasis reduction and higher levels of cancer cell differentiation compared to non-targeting controls." (PMID 37370745, 2023). "Subsequently, MALAT1 activates AGR2 transcription by recruiting E2F1 to increase the resistance of breast cancer cells to adriamycin and promotes cell proliferation and metastasis." (PMID 37901333, 2023). "MALAT1 is shown to control the growth, invasion, migration, as well as metastasis of hepatocellular cancer cells, cervical cancer cells, breast cancer cells, ovarian cancer cells, as well as colorectal cancer cells." (PMID 36934373, 2023). "The lncRNA TALAM1 is the natural antisense transcript (NAT) at the MALAT1 locus, and it is involved in the migration and invasion of breast cancer cells." (PMID 37754231, 2023). "Colon and breast cancer overexpress MALAT1 and stimulate proliferation by sponging miR-101-3p and miR-129-5p, respectively." (PMID 37190145, 2023). "On the other hand, when analyzing the RNA sequencing data (The Cancer GenomeAtlas), Kim encountered the lowest MALAT1 expression levels in more aggressivetumors; MALAT1 expression in breast cancer cells was lower than that in normaltissue." (PMID 37538803, 2023).
breast cancer (continued). "As for oncogenes, one study showed that METTL3 up-regulated MALAT1 expression to facilitate breast cancer cell migration and invasion via the MALAT1/miR-26b/HMGA2 axis." (PMID 37437245, 2023). "In a Slug and ZEB2 protein-dependent way, the lncRNA MALAT1 interacts with miR-204, leading to breast cancer growth via metastasis." (PMID 37245177, 2023). "According to the data reported previously, MALAT1 can be used as a promisingbiomarker in the clinical diagnosis and prognosis of aggressive breast cancer.Findings on the MALAT1 expression level can be a prognostic factor." (PMID 37538803, 2023). "MALAT1 is highly expressed in breast cancer and negatively correlated with the survival of patients." (PMID 37901333, 2023). "MicroRNA-561-3p (miR-561-3p), as a tumor suppressor, has been reported to play a role in preventing cancer cell progression, and MALAT1 (Lnc-RNA) have also been demonstrated to promote malignancy in various cancers, such as breast cancer (BC)." (PMID 37244966, 2023). "For example, MALAT1 leads to the epithelial-to-mesenchymal transition program through a phosphatidylinositide-3 kinase-AKT pathway in breast cancer, and thus MALAT1 is significantly downregulated in breast cancer tissues and cell lines." (PMID 36530425, 2022). "At the same time, in serum samples from patients with breast cancer, lncRNA MALAT1 is expressed significantly higher than in benign breast diseases." (PMID 35310927, 2022). "MALAT1 has been demonstrated to be abnormally regulated and exhibits prognostic significance in several cancers, including hepatocellular carcinoma, breast cancer, colorectal cancer, and gastric cancer as well as esophageal cancer 7-9." (PMID 35517413, 2022). "In a similar fashion the use of MALAT1 targeting ASOs was capable of blocking breast cancer progression via MALAT1 knockdown." (PMID 35788171, 2022). "More recently, three articles have shown that MALAT1, discovered initially in lung adenocarcinomas increase proliferation and invasion of breast cancer cells." (PMID 35626715, 2022). "In breast cancer, modulation of several lncRNAs contribute to the stemness phenotype, including well-known non-coding RNAs such as MALAT-1, HOTAIR and H19." (PMID 35626715, 2022). "Metformin upregulates the expressions of lncRNA MALAT1 and ER stress genes, while MALAT1 knockdown in metformin-treated breast cancer cells shows reduced phosphorylation of c-Myc." (PMID 36230902, 2022). "By contrast, Malat1 oncogene function in breast cancer resulted in upregulation of Cdc42 by targeting and binding miR-1, which is capable of recognizing the Cdc42 3′UTR and triggering its mRNA degradation." (PMID 35447891, 2022). "Knockout of MALAT1 in human breast cancer cells also promoted metastasis and was reversed by re-adding MALAT1 expression." (PMID 35740618, 2022). "The analysis did not point to any PUMILIO target genes significantly co-expressed with the MALAT1 or LINC00504 in breast cancer samples." (PMID 36412911, 2022). "MALAT1 has also been employed therapeutically in mouse models of lung and breast cancer where ASO-mediated silencing, significantly impairs tumor growth and metastasis formation." (PMID 35814429, 2022). "Recently, a highly conserved lncRNA called MALAT1 was found to promote pro-metastatic potential in breast cancer cells by upregulating EEF1A1 expression via epigenetic modulation of the promoter." (PMID 35456960, 2022). "In syngeneic, xenograft, and transgenic models, overexpression of lncRNA MALAT1 has been found to inhibit breast cancer metastasis." (PMID 35592755, 2022). "Although the oncogenic functions of MALAT1 have been reported in malignancies such as colorectal and liver cancer, more recent studies have highlighted the tumor suppressive role of MALAT1 against the growth and metastasis of glioma and breast cancer cells." (PMID 36084949, 2022).
breast cancer (continued). "For instance, expression of lncRNA MALAT1 was found to be significantly up-regulated in clinical breast cancer samples and negatively correlated with overall survival in in-situ carcinoma." (PMID 36685962, 2022). "In breast cancer, lncRNA MALAT1 sequesters miR-140 in order to upregulate VEGFA expression to promote tumor angiogenesis." (PMID 36010595, 2022). "METTL3 targeted MALAT1/miR-26b/HMGA2 axis and caused EMT and promotion of migration and invasion in breast cancer." (PMID 36212476, 2022). "MALAT1 has previously been described as an oncogene to promote metastasis across various cancers while recent studies showed that overexpression of MALAT1 suppresses the metastatic ability of breast cancer cells." (PMID 36203193, 2022). "Ligand administration is translated into the downregulation of Malat1 expression both in the cell lines of breast cancer and the branching morphogenesis in a mammary tumor model by inducing structural changes." (PMID 35054945, 2022). "The expression of lncRNA MALAT1 is associated with ERAT1 breast tumors and lower recurrence-free survival (RFS), and lncRNA MALAT1 can promote the occurrence and development of breast cancer by up-regulating the WNT/W-catenin (CTNNB1) pathway." (PMID 35706002, 2022). "MALAT1 levels were shown to be significantly related to breast cancer development and invasive capacity, indicating that MALAT1 acts as a metastasis suppressor." (PMID 35756601, 2022). "In fact, functional roles of MALAT1 have been elucidated in mouse models of breast cancer, however, variable data has been seen between studies possibly due to differences in the approach adopted for knockout strategies." (PMID 36230680, 2022). "Only few cancer types (breast cancer, esophageal carcinoma, sarcoma, thymoma and uveal melanoma) have a reduced expression level of MALAT1." (PMID 35723379, 2022). "HIF1A and HIF-2α can transcriptionally activate hypoxia-responsive lncRNA MALAT1 to enhance the migration of breast cancer cells." (PMID 36230902, 2022). "Not only this but also another group used the MMTV (mouse mammary tumor virus)-PyMT mouse mammary carcinoma model to assess the proliferative and metastatic potential of MALAT1." (PMID 36387279, 2022). "We have also evaluated, in the same experimental conditions as above, the expression level of VEGFA isoforms, which we have previously reported to be affected by MALAT1 subnuclear localization in breast cancer cells." (PMID 34530916, 2021). "Power analysis was carried out to assess the diagnostic value of PVT1, HOTAIR, NEAT1, MALAT1, PAI-1, and OPN in breast cancer." (PMID 33670447, 2021). "A large amount of research has reported that aberrantly expressed MALAT1 was involved in a variety of cancers, such as breast cancer metastasis, colon cancer, and non-small cell lung cancer." (PMID 34295352, 2021). "Although hypoxia-inducible factor was a major regulator of the non-coding and coding transcriptome in hypoxia, the regulatory mechanism of MALAT1 in breast cancer cells remains to be clarified." (PMID 34012919, 2021). "In contrast, eNEMAL was upregulated in response to hypoxia all other cancer cell lines, demonstrating that this enhancer is hypoxic-responsive in breast cancer and its upregulation under hypoxia corresponds with that of MALAT1." (PMID 34019552, 2021). "There have been numerous other reports of MALAT1 regulating multiple modulators and enhancing the EMT and stemness phenotype, which underlines its importance in breast cancer progression." (PMID 33414456, 2021). "On the other hand, a recent study by Kim and colleagues showed that MALAT1 levels inversely correlate with breast cancer progression and metastatic ability in transgenic, xenograft and syngeneic models." (PMID 33573289, 2021). "PTEN, a well-known tumor suppressor, regulates MALAT1 expression by potentially sponging oncogenic miRNAs, including miR-17 and miR-20a in breast cancer." (PMID 33987091, 2021).
breast cancer (continued). "MALAT1 has been shown to be a prognostic marker in TNBC, and implicated in therapeutic resistance and metastasis in breast cancer." (PMID 34681087, 2021). "Previously, we used next-generation sequencing (NGS) technology to identify oxygen-responsive lncRNAs in MCF-7 breast cancer cells and identified MALAT1 as one of the top five up-regulated lncRNAs under hypoxia." (PMID 34012919, 2021). "Serum HOTAIR level was found to be positively correlated with NEAT1 and MALAT1 levels in the breast cancer patients (r = 0.35, p < 0.05 and r = 0.51, p < 0.001, respectively)." (PMID 33670447, 2021). "Since the suppressive role of Malat1 on metastatic ability of breast cancer in mouse has been reported, more experiments in animal studies and clinical trials are still warranted to explore the MALAT1 pathway as a therapeutic target for breast cancer." (PMID 34012919, 2021). "For example, MALAT1 inhibits breast cancer metastasis and MALAT1 promotes angiogenesis in breast cancer." (PMID 34113575, 2021). "The significance of serum PVT1, HOTAIR, NEAT1, MALAT1, PAI-1, and OPN levels as potential diagnostic biomarkers for breast cancer was assessed using a ROC curve." (PMID 33670447, 2021). "The low expression of miR-206 and high expression of LINC00276 and MALAT1 were significantly correlated with the poor prognosis in breast cancer." (PMID 34457116, 2021). "In this study, we analyzed the serum expression levels of lncRNAs PVT1, HOTAIR, NEAT1, and MALAT1, and their associated proteins, PAI-1, and OPN, in breast cancer patients compared to fibroadenoma patients and healthy subjects." (PMID 33670447, 2021). "MALAT1 is one of the first identified cancer‐related lncRNA, and increasing evidences point out that it acts as a biomarker of numerous cancers, including breast cancer." (PMID 34164906, 2021). "MALAT1, which had a degree of 51, contributes significantly to cancer initiation and progression in breast cancer." (PMID 33983999, 2021). "MALAT1 overexpression is positively correlated with tumor progression and metastasis of various tumor types, including breast cancer." (PMID 33558499, 2021). "Taken together, these data demonstrated that the -20 kb enhancer which forms long-range chromatin interactions at the MALAT1 locus is transcriptionally active, generating an eRNA in breast cancer cells." (PMID 34019552, 2021). "It has been demonstrated that serum MALAT1 levels in breast cancer patients are markedly higher than those in patients with benign breast disease." (PMID 34527584, 2021). "LncRNA MALAT1 has previously been regarded as a metastasis-promoting factor in various tumors, but it is a metastasis-suppressing factor in breast cancer through binding and inactivating the pro-metastatic transcription factor TEAD." (PMID 34295922, 2021). "We can conclude that the m6A methyltransferase METTL3 controls epithelial-mesenchymal transition of breast cancer through the MALAT1/miR-26b/HMGA2 axis." (PMID 34419065, 2021). "Downregulation of EMT-like transition and inhibition of cell invasion was also observed in TNBC cells, MB231, upon MALAT1 knockdown, suggesting knockdown of MALAT1 inhibits EMT in different subtypes of breast cancer as well." (PMID 32708561, 2020). "Different conclusions from two knockdown studies confound the role of MALAT1 in breast cancer pathogenesis." (PMID 32708561, 2020). "Hazard ratio (HR) and odds ratio (OR) with 95% confidence interval (CI) were calculated to evaluate the effect of MALAT-1 expression on the survival outcomes and clinicopathological features of breast cancer." (PMID 32700729, 2020). "MALAT1 has therefore been proposed to function as a tumor suppressor in colorectal and breast cancers." (PMID 32174966, 2020). "We showed in this study that the upregulation of MALAT1 decreased trastuzumab resistivity in HER2+ breast cancer cells." (PMID 32708561, 2020).